AZIN1 (antizyme inhibitor 1)
Diseases named in the same sentence as AZIN1 in open-access papers (continued):
Sharing a sentence is not in itself a finding about the gene and the disease.
prostate carcinoma (4 papers, 2018 to 2025). A carcinoma that arises from epithelial cells of the prostate gland. "And RNA-edited AZIN1 leads to enhanced cellular aggressiveness, and is associated with worse prostate cancer outcomes." (PMID 38169396, 2024). "Taken together, these results demonstrate an association between AZIN1 RNA editing and an increased incidence of tumor progression in prostate cancer patients." (PMID 36202978, 2022). "First, the integrative copy-number aberration and gene expression analyses indicated that AZIN1 gene expression increased in a focal amplification of 8q22.3 and associated with metastatic recurrence, which identified AZIN1 as a novel driver of metastatic progression in high-risk prostate cancer." (PMID 38169396, 2024). "Importantly, during longitudinal follow-up in two independent cohorts of men with primary prostate cancer, increased AZIN1 editing and nuclear localization were associated with a higher risk of tumor recurrence following surgery." (PMID 36202978, 2022). "Taken together, our data indicate that the single S367G substitution in AZIN1 caused by RNA editing is sufficient to induce nuclear localization of AZIN1 and support the conclusion that the nuclear AZIN1 observed in the prostate cancer sections was the edited form." (PMID 36202978, 2022). "Furthermore, we found that AZIN1 editing is common in primary prostate tumors, confirmed the increased presence of edAZIN1 in high Gleason score (7+) prostate cancers, and observed that increased editing of AZIN1 is associated with a higher Gleason score at the time of resection." (PMID 36202978, 2022). "We have previously reported that increased AZIN1 expression predicts aggressiveness and poor outcome in prostate cancer." (PMID 39962590, 2025). "We observed a striking difference in AZIN1 localization in clinical specimens of primary prostate cancer compared to benign paired control samples and observed a correlation between the editing and nuclear localization of AZIN1." (PMID 36202978, 2022). "Together, these data indicate that AZIN1 editing is a common mechanism by which prostate cancers develop enhanced aggressiveness." (PMID 36202978, 2022). "Using proximity ligation assay, we confirmed that each of these proteins associates with AZIN1 in PC3 and DU145 prostate cancer cells." (PMID 36202978, 2022). "They suggest AZIN1 transport into the nucleus is a key event leading to poorer outcomes in patients with prostate cancer." (PMID 36202978, 2022). "Work spearheaded by Aram Ghalali and led by Michael Rogers and Bruce Zetter at Harvard Medical School, Boston, USA, explored the consequences of AZIN1 RNA editing in prostate cancer." (PMID 36202978, 2022). "To establish the clinical relevance of AZIN1 editing in prostate cancer, we studied different patient populations using three orthogonal methods." (PMID 36202978, 2022). "AZIN1 is upregulated in human prostate cancers, and this upregulation correlates with increased tumor aggressiveness." (PMID 36202978, 2022). "On the other hand, the knocking down of AZIN1 using shRNA in both human and rat prostate cancer cell lines decreased the ability of these cells to form tumors in vivo, after subcutaneous injection into nude mice." (PMID 30304856, 2018). "Next, high edited AZIN1 could also be a predictor of worse prognosis in endometrial cancer and prostate cancer." (PMID 38169396, 2024). "We found that the presence of edAZIN1 induces increased proliferation, invasion, and colony formation of prostate cancer cells, whereas the presence of an uneditable AZIN1 allele did not." (PMID 36202978, 2022). "In this report, we investigate the consequences of AZIN1 RNA editing in prostate cancer." (PMID 36202978, 2022). "Taken together, these findings strongly suggest that the subcellular localization of AZIN1 may be a more robust marker for prostate cancer than total AZIN1 expression." (PMID 36202978, 2022).
prostate carcinoma (continued). "To determine whether editing of AZIN1 mRNA results in protein “gain of function”, we transiently overexpressed three different forms of AZIN1 in prostate cancer cells." (PMID 36202978, 2022). "The edited AZIN1 mRNA transcript was detected in 94% of the 50 prostate cancer samples tested." (PMID 36202978, 2022). "AZIN1 enhanced migration of prostate cancer cells independent of polyamines, by modulating production of matrikines released from type IV collagen." (PMID 38169396, 2024). "However, the role of AZIN1 in human prostate cancer has not been explored in depth." (PMID 36202978, 2022).
glioblastoma (3 papers, 2022 to 2025). The most malignant astrocytic tumor (WHO grade IV). "We conducted AZIN1 immunohistochemistry using tissue microarrays composed of 69 cases of MB, 38 cases of astrocytoma, 14 cases of glioblastoma, 6 cases of oligodendroglioma, 1 case of ependymoma, 31 controls (consists of 3 cases of cancer adjacent brain tissue and 28 normal brain tissues)." (PMID 39962590, 2025).
lung carcinoma (3 papers, 2012 to 2024). "As an important target of ADAR1, Antizyme inhibitor 1 (AZIN1) is involved in forming various cancers, including colorectal and lung cancer." (PMID 39006762, 2024). "Expression analysis reveals that hypoxia induced lung cancer related biomarkers, HIF and its modulating proteins (TGM2, CSNK1A1, CTNNA1, NAMPT/Visfatin, TNFRSF1A, ETS1, SRC-1, FN1, APLP2, DMBT1/SAG, AIB1 and AZIN1) are significantly down regulated." (PMID 23122428, 2012).
colon cancer (2 papers, 2014 to 2022). "To assess the effect of edited AZIN1 in CRC progression, we performed xenograft experiments using AZIN1 overexpressing HCT 116 colon cancer cells mixed with HUVEC to confirm our in vitro findings." (PMID 35365616, 2022).
acute kidney injury (1 paper, 2024). Sudden and sustained deterioration of the kidney function characterized by decreased glomerular filtration rate, increased serum creatinine or oliguria. "Adenosine-to-inosine editing of antizyme inhibitor 1 (AZIN1) promotes recovery from acute kidney injury by enhancing metabolic flexibility." (PMID 38954486, 2024). "We found that AZIN1 editing is common in non-cancerous kidney tissues, including those with diabetic kidney disease, acute kidney injury (AKI), and even reference nephrectomy." (PMID 38954486, 2024).
brain cancer (1 paper, 2025). A primary or metastatic malignant neoplasm affecting the brain. "Our initial analysis of these childhood brain cancers revealed variable AZIN1 expression in MB with some patient samples exhibiting high AZIN1 expression while others having no detectable expression." (PMID 39962590, 2025).
brain tumors (1 paper, 2025). "While AZIN1 has been associated with several tumors, there are no standalone studies of AZIN1 in brain tumor pathogenesis - an important distinction of the work presented here, given the outsized impact of brain tumors on pediatric life expectancy." (PMID 39962590, 2025).
Cirrhosis (1 paper, 2016). A chronic disorder of the liver in which liver tissue becomes scarred and is partially replaced by regenerative nodules and fibrotic tissue resulting in loss of liver function. "Moreover, a cirrhosis risk score consisting of SNPs in 7 genes (AP3S2, AQP2, AZIN1, DEGS1, STXBP5L, TLR4, and TRPM5) has been shown to predict fibrosis progression in HCV infected patients." (PMID 26950933, 2016).
craniosynostosis (1 paper, 2023). Craniosynostosis is defined as the premature fusion of one or more cranial sutures leading to secondary distortion of skull shape resulting in skull deformities with a variable presentation. "Among the four novel loci (ZIC1, PRKAR1A, AZIN1/ATP6V1C1, GLRX3), there are factors implicated in intramembranous ossification and as we show, inherent to craniosynostosis processes." (PMID 37402774, 2023).
diabetes (1 paper, 2021). "AZIN1 was downregulated in responders; AZIN1 promotes polyamine production, essential for cell growth, and differentiation, but AZIN1 overactivation can increase the invasive potential of fibroblasts and can lead to cancer, inflammation or diabetes." (PMID 33746955, 2021).
endotoxemia (1 paper, 2024). "We found that A-to-I editing of antizyme inhibitor 1 (AZIN1), a positive regulator of polyamine biosynthesis, serves as a particularly useful temporal landmark during endotoxemia." (PMID 38954486, 2024). "To understand the role of AZIN1 editing and polyamine metabolism in the kidney, we next interrogated a well-characterized animal model of endotoxemia." (PMID 38954486, 2024). "The rate of Azin1 editing significantly increased from 0% to over 40% with the progression of endotoxemia." (PMID 38954486, 2024). "Finally, we examined the role of Azin1 A-to-I editing in the endotoxemia model and confirmed the renoprotective effects of A-to-I–locked state." (PMID 38954486, 2024). "Furthermore, Ribo-Seq analysis (ribosome profiling) showed that Azin1 translation remained nearly constant throughout the course of endotoxemia." (PMID 38954486, 2024). "Thus, editing of Azin1 at this precise time point may serve as a clock to stage endotoxemia." (PMID 38954486, 2024).
esophageal cancer (1 paper, 2025). A primary or metastatic malignant neoplasm involving the esophagus. "ADAR1-driven editing of coding transcripts—such as antizyme inhibitor 1 (AZIN1) (serine→glycine substitution)—enhances protein oncogenic potential across colorectal, endometrial, gastric, liver, and esophageal cancers." (PMID 41169479, 2025).
esophageal tumors (1 paper, 2016). "Besides, AZIN1 expression was significantly increased in esophageal tumors compared with their matched nontumor specimens." (PMID 27687780, 2016).
kidney cancer (1 paper, 2024). Primary or metastatic malignant neoplasm involving the kidney. "Interestingly, AZIN1 was lower in all types of kidney cancer, as seen in KICH, KIRC, and KIRP." (PMID 39140420, 2024).
kidney injury (1 paper, 2024). Trauma to the kidney. "Because Azin1 edited status had a significant effect on glycolysis, we examined its role in an ischemia/reperfusion model of kidney injury." (PMID 38954486, 2024).
lymph node metastasis (1 paper, 2018). "Logistic regression analysis revealed that hyper-editing status of AZIN1 RNA was an independent risk factor for lymph node metastasis in GC patients [hazard ratio (HR):3.03, 95% CI 1.19–7.71, P = 0.02]." (PMID 30563560, 2018). "Finally, our data revealed that higher levels of AZIN1 RNA editing were an independent risk factor for lymph node metastasis (LNM) in patients with GC, highlighting its biomarker potential in the identification of high-risk patients that may experience tumor recurrence post-surgical treatments." (PMID 30563560, 2018). "Increased levels of AZIN1 RNA editing were significantly correlated with established clinicopathological factors such as advanced T stage (P = 0.031), presence of lymph node metastasis (LNM; P = 0.021), and higher TNM stages (P = 0.028) in GC patients." (PMID 30563560, 2018). "Our study also demonstrated an intimate correlation between AZIN1 RNA editing levels and lymph node metastasis in GC patients." (PMID 30563560, 2018). "Increased AZIN1 RNA editing and ADAR1 over-expression were significantly correlated with key clinicopathological factors, such as advanced T stage, presence of lymph node metastasis, distant metastasis, and higher TNM stages in GC patients." (PMID 30563560, 2018).
medulloblastoma (1 paper, 2025). A malignant, invasive embryonal neoplasm arising from the cerebellum. "We found that overexpression of AZIN1 in medulloblastoma cells induces phenotypically aggressive features." (PMID 39962590, 2025). "Here, we investigated the role of AZIN1 expression in medulloblastoma." (PMID 39962590, 2025).
mesothelioma (1 paper, 2022). A usually malignant and aggressive neoplasm of the mesothelium which is often associated with exposure to asbestos. "The positive correlation between AZIN1 editing and ADAR1 mRNA levels was also found in a large panel of primary mesothelioma cultures, indicating that AZIN1 editing most likely reflects ADAR1 abundancy." (PMID 36221913, 2022).
Myocardial fibrosis (1 paper, 2020). "Further studies show that miR-433 can simultaneously inhibit the expression of AZIN1 and JNK1 and activate TGF-β1 pathway, and ERK and p38 kinase, thereby promoting myocardial fibrosis." (PMID 31868204, 2020).
myocardial infarction (1 paper, 2020). Gross necrosis of the myocardium, as a result of interruption of the blood supply to the area, as in coronary thrombosis. "For instance, forced expression of miR-433 contributed to cardiac fibrosis and ventricular dysfunction following myocardial infarction possibly through targeting AZIN1 and JNK1, which functioned as an anti-fibrosis factor in the progression of cardiac fibrosis." (PMID 32812641, 2020).
osteosarcoma (1 paper, 2025). A usually aggressive malignant bone-forming mesenchymal neoplasm, predominantly affecting adolescents and young adults. "Given AZIN1’s known role in regulating ODC1 stability and activity, we hypothesized that AZIN1 overexpression underlies the dysregulated arginine-polyamine metabolism characteristic of osteosarcoma." (PMID 40246846, 2025). "We performed a comprehensive analysis of RNA-seq data from 143B and U2-OS osteosarcoma cells with AZIN1 knockdown to investigate how polyamine metabolism modulates the osteosarcoma immune microenvironment." (PMID 40246846, 2025). "Collectively, these results highlight the pivotal role of the AZIN1-polyamine-MYC axis in governing cell cycle progression in osteosarcoma." (PMID 40246846, 2025). "Collectively, these findings underscore the pivotal role of the AZIN1-polyamine axis in osteosarcoma and support developing immunotherapeutic strategies that target polyamine metabolism to overcome resistance and enhance treatment efficacy." (PMID 40246846, 2025). "To investigate how AZIN1 influences osteosarcoma cell proliferation, we performed RNA sequencing on 143B, and U2-OS cells stably knocked down for AZIN1 and compared the results to control cells." (PMID 40246846, 2025). "In light of these insights, targeting the AZIN1-polyamine axis presents a promising strategy for combating osteosarcoma." (PMID 40246846, 2025). "Taken together, these findings highlight the critical role of AZIN1-driven polyamine synthesis in modulating the immune microenvironment, which in turn influences the immunogenicity of osteosarcoma and its vulnerability to T-cell-mediated cytotoxicity." (PMID 40246846, 2025). "Accordingly, A2M4 TCR-T cells co-cultured with AZIN1-knockdown osteosarcoma cells secreted significantly more IFN-γ than those co-cultured with shControl cells." (PMID 40246846, 2025). "Taken together, these results highlight the pivotal function of AZIN1 in osteosarcoma proliferation and underscore its potential as a therapeutic target." (PMID 40246846, 2025). "To test this hypothesis, we generated 143B and U2-OS osteosarcoma cell lines with stable AZIN1 knockdown and conducted cell viability assays." (PMID 40246846, 2025). "Collectively, our findings establish a pivotal role for the AZIN1-polyamine axis in osteosarcoma proliferation and immune evasion, and support the development of novel immunotherapeutic strategies targeting polyamine biosynthesis to combat this aggressive cancer." (PMID 40246846, 2025). "Given the established function of polyamines in cell cycle regulation, we hypothesized that AZIN1 promotes the osteosarcoma cell cycle by modulating ODC1 activity and, consequently, polyamine synthesis." (PMID 40246846, 2025). "Notably, polyamine supplementation can restore these tumorigenic features that were lost upon AZIN1 knockdown, underscoring the tight functional interplay between polyamines and MYC in osteosarcoma pathophysiology." (PMID 40246846, 2025).
renal cell carcinoma (1 paper, 2024). "In addition, some reference nephrectomy samples were derived from tissues adjacent to renal cell carcinoma, which may also influence AZIN1 A-to-I editing status." (PMID 38954486, 2024).
schizophrenia (1 paper, 2025). A major psychotic disorder characterized by abnormalities in the perception or expression of reality. "A translational convergent functional genomics study identified the gene AZIN1, which encodes AZIN1, as a candidate gene for schizophrenia, providing genetic support for these findings." (PMID 41346597, 2025).